AKT1 (AKT serine/threonine kinase 1)
Diseases named in the same sentence as AKT1 in open-access papers (continued):
Sharing a sentence is not in itself a finding about the gene and the disease.
meningioma (continued). "PIK3CA co-mutations are also found in meningiomas with TRAF7 mutations but without KLF4 mutations, and PIK3CA is also associated with activation of mTOR signaling, as with AKT1 alterations." (PMID 41372821, 2025). "CDKN2A deleted meningiomas did not harbour SMARCB1, AKT1, PIK3CA, SMO, POLR2A, or RB1 somatic mutations." (PMID 37093270, 2023). "On the other hand, there are no reports of meningiomas with only AKT1 or KLF4 mutations, suggesting that a missense TRAF7 alteration is pre-requisite for AKT1 or KLF4 mutations to cause tumor." (PMID 36937440, 2023). "Furthermore, several typical meningioma locations have distinct related genomic markers (e.g., anterior skull base: SMO, AKT1E17K, TRAF7; central skull base: AKT1, KLF4, TRAF7, POLR2A, Convexity: NF-2, LOH chromosome 22, BAP1)." (PMID 38017560, 2023). "The combination is intriguing: AKT1/TRAF7 mutations are associated with meningothelial histology and basal localization, while KLF4/TRAF7 mutations are highly specific for secretory meningioma without any predominant localization." (PMID 35984495, 2022). "SMO- and AKT-1-mutated meningiomas have shown to recur more frequently, compared with meningiomas lacking SMO and AKT1 mutations." (PMID 35565385, 2022). "While KLF4 or AKT1 mutations almost always co-occurred with TRAF7 mutations, they did not occur together; SMO-mutated meningiomas all harbored the activating L412F mutation." (PMID 31652973, 2019). "POLR2A-mutant meningiomas do not exhibit mutations in other meningeal driver genes, such as NFE2, TRAF7, KLF4, AKT1, or SMO." (PMID 30279357, 2018). "Additionally, alterations in other genes such as SMO, AKT1, TRAF7, and KLF4 have been identified, particularly in non-NF2 mutant meningiomas, indicating a heterogeneous molecular landscape that may influence both prognosis and treatment response." (PMID 41007735, 2025). "SMO mutations occur in about 5% of meningiomas which do not show alterations in NF2, AKT1 and KLF1." (PMID 36181606, 2023). "Merlin-intact meningiomas can encode somatic short variants (SSVs) targeting TRAF7, PIK3CA, AKT1, KLF4, or the Hedgehog pathway, but some of these variants may be passenger mutations that do not influence meningioma tumorigenesis." (PMID 36993679, 2023). "Moreover, a national Alliance-sponsored cooperative group phase II clinical trial evaluated the efficacy of SMO, AKT1, and FAK inhibitors for recurrent or progressive meningiomas with targetable alterations in SMO, AKT1, and NF2, respectively (NCT02523014/A071401)." (PMID 35712491, 2022). "In addition, 1–5% of meningiomas without alterations in NF2 and AKT1, harbor mutations in the SMO gene, which encodes smoothened homolog, a member of the Hedgehog signaling pathway." (PMID 35565385, 2022). "This may be in part because the AKT1 and PiK3CA mutations are rare, found only in 9% and 7% of WHO grade 1 meningiomas without NF2 abnormalities." (PMID 36139608, 2022). "Notably, the PIK3CA-mutant meningiomas lacking mutations in NF2, AKT1, and SMO, tend to express TRAF7 mutations." (PMID 35565385, 2022). "However, mutations in TRAF7 can be present in isolation, though often they can co-occur with KLF4, AKT1, or PIK3CA mutations, whereas mutations in SMO and POLR2A are usually mutually exclusive Interestingly, the meningiomas arising from SMO and AKT1-MTOR aberrations often arise in the skull base." (PMID 33194703, 2020). "The AKT1 E17K was reported in WHO I meningioma, rare in WHO II and absent in anaplastics." (PMID 29391485, 2018). "Comparison of the AKT1 E17K and NF2-negative mRNA expression levels determined that IL-10 mRNA was significantly elevated in the grade I NF2 negative meningioma tissues." (PMID 32070062, 2020).
meningioma (continued). "A second subgroup contained AKT1 (n = 26), PIK3CA (n = 14) and SMO (n = 7) mutant skull-based meningiomas, and a third mixed subgroup included 237 meningiomas with a heterogeneous spectrum of low frequency and non-recurrent alterations." (PMID 33087175, 2020). "NF2 mutations were found in 44% of the cases, while common genetic alterations in meningiomas of other locations (TRAF7, AKT1, SMO, KLF4, PIK3CA, and TERT) were lacking in non-NF2-associated cases." (PMID 31470906, 2019). "SMO and AKT1 in particular are primarily found in meningothelial or transitional WHO grade I meningiomas, are rare in WHO grade II lesions, and absent in WHO grade III meningiomas." (PMID 34638590, 2021).
cardiac hypertrophy (125 papers, 2009 to 2026). "Studies have shown that transient activation of Akt1 leads to reversible cardiac hypertrophy, which is associated with reduced expression of Lrg1 (GDS2304 / 1417290_at / Lrg1)." (PMID 28509980, 2015). "However, a different observation showed that AKT1-deficient mice result experience increased susceptibility to hypertrophic stimuli and more profound cardiac hypertrophy in response to aortic constriction." (PMID 34540911, 2021). "Also, Akt1 deficiency showed its significant role in regulation of cardiovascular function as Akt1 regulates the physiological cardiac hypertrophy such as in exercise-induced cardiac hypertrophy." (PMID 30444896, 2018). "The DEGs associated with cardiac hypertrophy were screened via bioinformatics analysis, and eight hub genes were identified, including Akt1, Lox, Timp1, Col1al, Spp1, Ccnd1, Mmp3, and Egfr, which might be a new target for the identification of cardiac hypertrophy." (PMID 36046382, 2022). "Leading kinases included AKT1, MAPK1, MYLK, INSR, and ABL1, all of which are implicated in stress response and cardiac hypertrophy, particularly under physiological conditions." (PMID 40725470, 2025). "At the intracellular level, insulin binds to the IR, activating the PI3K/Akt pathway, with Akt1 mediating cardiac hypertrophy and normal postnatal growth." (PMID 41007785, 2025). "AKT1 plays a critical role in the regulation of cardiac function, including the control of cardiac hypertrophy, apoptosis (programmed cell death), and contractility." (PMID 37893458, 2023). "Transverse coarctation of the aorta occurs in hypertrophy and heart failure under pressure overload, and Akt1 hyperactivation occurs in left ventricular cardiomyocytes." (PMID 36959563, 2023). "In contrast, deficiency of AKT1 leads to resistance to vascular senescence, whereas increased AKT1 activity induces cardiac hypertrophy." (PMID 35111368, 2022). "AKT1 deficiency can prolong the life span in the DKO mouse model, improve cardiac function and reduce myocardial hypertrophy." (PMID 35287352, 2022). "To confirm this is the only way that CRAMP functions in cardiac hypertrophy, we used AKT1 siRNA to silence AKT1 in NRCMs." (PMID 32029708, 2020). "Our results revealed the relationship between Met and the AKT1–SERCA2 signaling pathway in AVP-induced pathological cardiac hypertrophy." (PMID 32489586, 2020). "Our results also suggest that AKT1 can be taken as a possible gene therapeutic target for the treatment of pathological cardiac hypertrophy and to improve heart function." (PMID 32489586, 2020). "Our results demonstrated that the AKT1–SERCA2 cascade served as an important regulatory pathway in AVP-induced pathological cardiac hypertrophy." (PMID 32489586, 2020). "Studies found that AKT1−/− mice developed greater cardiac hypertrophy in response to aortic constriction." (PMID 32029708, 2020). "Further, when the activation of AKT1 was increased, pathological cardiac hypertrophy and fibrosis were ameliorated in HF mice." (PMID 32029708, 2020). "In vitro, the chronic activation of Akt1 gene expression in mice can induce adaptive cardiac hypertrophy and dilated cardiomyopathy." (PMID 30995779, 2019). "Our results do not seem consistent with previous studies, showing that chronic Akt1 activation, which activates mTORC1, has been shown to worsen aging-induced cardiac hypertrophy and impair myocardial contractile." (PMID 28115595, 2017). "Taken together, these results indicate that CYP2J2 or its metabolite 11,12‐EET induced the nuclear accumulation of p‐Akt1 via AMPKα2 to prevent development of cardiac hypertrophy." (PMID 27416746, 2016). "In particular, Akt1 has been demonstrated to play an antagonist role against pathological cardiac hypertrophy, which is an inevitable precursor of heart failure." (PMID 26989696, 2016).
cardiac hypertrophy (continued). "In the heart, MtorC1 is an important modulator of Akt/PKB regulated cardiac hypertrophy, and rapamycin treatment was able to prevent the hypertrophy induced by overexpressing a constitutively activated Akt1." (PMID 23342106, 2013). "Short-term Akt activation in inducible Akt1 transgenic mice induces physiological cardiac hypertrophy with maintained vascular density, indicating that coronary angiogenesis is enhanced to keep pace with the growth of the myocardium." (PMID 19737384, 2009). "Moreover, Akt1 played an essential role in mediating physiological cardiac growth and attenuated pathological cardiac hypertrophy." (PMID 39611167, 2024). "During cardiac hypertrophy, the overexpression of miR-99 facilitates the transition from physiological hypertrophy to pathological hypertrophy, and silencing of miR-99 has the opposite effect, through the regulation of the Akt-1 pathway." (PMID 34211501, 2021). "Mechanistically, Akt1 directly promotes protein translation, in part by inhibiting GSK3β activity, which negatively regulates eukaryotic translation initiation factor 2B and thereby represses cardiac hypertrophy." (PMID 33400052, 2021). "Although our study suggests that the AKT1–SERCA2 cascade exerts important functions in AVP-induced pathological cardiac hypertrophy, there may be some differences with those in vivo." (PMID 32489586, 2020). "In this regard, short-time activation of the Akt1 gene in the heart resulted in adaptive cardiac hypertrophy with enhanced coronary angiogenesis and preserved contractility, whereas cardiac dilatation and failure was observed in response to chronic, long-term Akt1 stimulation." (PMID 30895179, 2019). "Others also point out that Akt1 is a critical mediator of pathological cardiac hypertrophy." (PMID 28115595, 2017). "We investigated whether CYP2J2 and its metabolites EETs protected against cardiac hypertrophy by activating AMPKα2 and Akt1." (PMID 27416746, 2016). "One study has shown that Akt1‐mediated protection against cardiac hypertrophy is dependent on ANP." (PMID 27416746, 2016). "Notably, it has been reported that T4 promotes the AKT1 signaling pathway in the heart, which in turn contributes to the cardiac hypertrophy observed in this model." (PMID 26146529, 2015). "LRG1 overexpression might be able to reverse cardiac hypertrophy induced by the activation of IGF1/PI3K/Akt1 pathway, exercise, pressure overload, and in α-TM E180G transgenic mice." (PMID 28509980, 2015). "Interestingly, it was observed that Akt1 can contribute detrimentally to cardiac hypertrophy whereas, in contrast, Akt2 slightly attenuated ischemia-induced cardiomyocyte apoptosis." (PMID 27713345, 2010). "In addition, SIRT3 stimulation can reduce ROS level and AKT1 signal and prevent myocardial hypertrophy, which may be one of the mechanisms of resveratrol inhibiting cardiac remodeling." (PMID 36120366, 2022). "In the present study, Ang II was found to induce myocardial hypertrophy, fibrosis, oxidative stress, and inflammation, as evidenced by alterations in the PI3K/AKT1/mTOR/ERK, TGF-β/Smad2/3, NF-κB, and NOX1 signaling pathways." (PMID 39715792, 2025). "More strikingly, when cardiac hypertrophy was provoked either by transverse aortic constriction (TAC) or AKT Serine/Threonine Kinase 1 (AKT1) overexpression in cardiomyocytes, inhibiting angiogenesis by soluble FKL1 was shown to prevent cardiac hypertrophy." (PMID 35874523, 2022). "Here, we investigated the effect of RES on ERK 1/2, p38-MAPK, Akt-1, and GSK-3β pathways which plays a critical role in cardiac hypertrophy and ventricular dilatation, myocyte survival, apoptosis, autophagy, and necrosis." (PMID 29109832, 2017). "The CYP2J2 metabolites, 11,12‐EET, activated AMPKα2 to induce nuclear translocation of p‐Akt1 selectively, which increased the production of ANP and therefore inhibited the development of cardiac hypertrophy." (PMID 27416746, 2016).
cardiac hypertrophy (continued). "In this present study, we predicted that AKT1 and MAPK3 might be the key targets of the active compound naringenin in Chenopodium during the prescreening process to regulate myocardial hypertrophy." (PMID 35281609, 2022). "Adaptive cardiac hypertrophy in response to exercise training has been abrogated in mice lacking Akt1, demonstrating the role of Akt1 in cardiac hypertrophy." (PMID 33670798, 2021). "Importantly, CYP2J2 and EET induced the formation of the AMPKα2β2γ1–pAkt1 complex, leading to the nuclear translocation of p‐Akt1, which, in turn, upregulated the expression of ANP, attenuating cardiac hypertrophy." (PMID 27416746, 2016). "Cardiac-specific overexpression of constitutive activated AKT mutant could lead to decompensation of hypertrophy; conversely, AKT1 knockout mice were resistant to cardiac hypertrophy." (PMID 27110236, 2016). "Most notably, AKT1-Ser473 phosphorylation as well as levels of phospho-ERK1/2, phospho-mTOR, and phospho-p38MAPK were significantly elevated in the Mat-Ob group, suggesting an active role of mTOR in the development of cardiac hypertrophy upon diet-induced maternal obesity." (PMID 30305865, 2018). "Our studies reveal a novel mechanism in which CYP2J2 and EETs enhanced Akt1 nuclear translocation through interaction with AMPKα2β2γ1 and protect against cardiac hypertrophy and suggest that overexpression of CYP2J2 might have clinical potential to suppress cardiac hypertrophy and heart failure." (PMID 27416746, 2016). "Liraglutide, a GLP-1 analog, significantly reduced cardiac hypertrophy and fibrosis and improved cardiac function in a non-diabetic animal model of cardiac hypertrophy induced by Ang II or pressure overload by modulation of PI3K/Akt1 and AMPKα signaling." (PMID 36834796, 2023).
schizophrenia (115 papers, 2007 to 2026). A major psychotic disorder characterized by abnormalities in the perception or expression of reality. "There is evidence that the AKT1 gene was initially identified as a potential susceptibility gene for schizophrenia." (PMID 41283305, 2025). "AKT1 levels in brain tissue have been previously associated with both schizophrenia and bipolar disorder, and although genetic associations exist, they do not pass genome-wide multiple-testing correction." (PMID 38306997, 2024). "Gene mutations associated with CP, such as AKT1 mutations, are also reportedly associated with the risk of developing schizophrenia." (PMID 36537061, 2023). "When assessed on a relatively larger sample, a significant association was found between the diagnosis of schizophrenia and an AKT1 haplotype which was predictive of lower AKT1 protein levels." (PMID 36979877, 2023). "Genetic studies have shown that an AKT1 haplotype associated with schizophrenia in humans resulted in low levels of AKT1 expression and greater sensitivity to sensorimotor gating disruption by amphetamine." (PMID 35525984, 2022). "Research has found a reduction of AKT1-associated pathways in the peripheral blood mononuclear cells of schizophrenia patients." (PMID 35844244, 2022). "In Akt1(±) mice that mimic the genetic deficiency in schizophrenia patients, sub-chronic treatment with lithium alleviated psychomotor agitation and depressive behavior, and restored impaired sensorimotor gating." (PMID 35126052, 2021). "Taking advantage of the Akt1 heterozygous mutant (Akt1+/−) mouse model of schizophrenia and Akt1-deficient cellular models, we focused on investigating the therapeutic potential of lithium in the alleviation of Akt1-related deficits." (PMID 31959776, 2020). "A genetic association between variants of the AKT1 gene and schizophrenia has been shown in several populations." (PMID 32265715, 2020). "Taking advantage of the Akt1 mutant mouse model of schizophrenia and Akt-deficient cellular models, we confirmed that Akt deficiency resulted in behavioral deficits in Akt1+/− female mice and neuromorphological changes in cell models." (PMID 31959776, 2020). "Schizophrenia, for example, has been associated with SNPs in AKT1 and AKT3, reduced AKT1 levels in patient brains, and pathogenic AKT signaling." (PMID 33325370, 2020). "Akt1, one of the Akt isoforms, has been independently identified as one of the schizophrenia-associated genes." (PMID 31819047, 2019). "Genetic studies have supported the association between AKT1 genetic variants and schizophrenia, suggesting that impaired AKT/GSK-3 signaling contributes to the pathogenesis of schizophrenia." (PMID 31191636, 2019). "It is remarkable that AKT1 has been originally identified as a possible susceptibility gene for schizophrenia." (PMID 30781836, 2019). "On the other hand, Akt1 and Akt3 have been identified as possible susceptibility genes for schizophrenia and Akt2 has been associated with anxiety- and depression-like behaviors." (PMID 31871542, 2019). "It has been reported that AKT1 gene polymorphisms are associated with schizophrenia, and antipsychotic drugs modulate the Akt/GSK-3 and Wnt signaling pathways in order to correct the deficits induced by the gene mutation." (PMID 29713286, 2018). "Akt protein dysregulation has been linked to schizophrenia, and, in addition, AKT1 genetic variations have been associated with increased psychotic symptoms after smoking cannabis." (PMID 29748632, 2018). "Mutations in AKT1 have been associated with schizophrenia, AKT2 with gliomas and AKT3 with brain growth." (PMID 29173281, 2017). "The gene encoding the serine-threonine kinase AKT1 has long been implicated in schizophrenia across multiple studies." (PMID 28804444, 2017). "Specifically, AKT1 is associated in humans with schizophrenia and abnormal PFC and hippocampal- structure and function." (PMID 28467426, 2017).